CRP (C-reactive protein)
Diseases named in the same sentence as CRP in open-access papers (continued):
Sharing a sentence is not in itself a finding about the gene and the disease.
Obesity (continued). "In summary, the present study documented gender, living area, age group, CRP concentration, and vitamin A status were associated with children and adolescents with overweight and obesity." (PMID 35379317, 2022). "Gender, living area, age, CRP concentration, and vitamin A status were associated with children and adolescents with overweight and obesity compared to low/normal BMI." (PMID 35379317, 2022). "Nappo reported that CRP levels are associated to higher body mass and overweight/obesity risk in a large population of European children." (PMID 35379317, 2022). "The associated factors of micronutrients and CRP of overweight and obesity were explored by multifactor analysis." (PMID 35379317, 2022). "In the present study, gender, age, living area, CRP concentration, and vitamin A status were associated with children and adolescents with overweight and obesity." (PMID 35379317, 2022). "Positive association was observed for leptin, CRP, fasting insulin, and estradiol, when comparing women with obesity or overweight versus normal weight." (PMID 35048536, 2022). "HFD-induced obesity of rats also caused systemic inflammation with an elevation of serum CRP levels and a significant increase in the serum levels of the inflammatory cytokines IL-6 and TNF-α." (PMID 35721744, 2022). "As CRP is indicator of inflammation and potential mediator of the obesity-cancer association, it is highly plausible that the continual worsening is attributable to obesity and insulin resistance observed in our sample." (PMID 35241143, 2022). "A recent study within the VIVA cohort demonstrated that the observed association between maternal obesity with offspring visual motor abilities and fine motor skills was mediated by maternal CRP." (PMID 36499584, 2022). "On the other side, human obesity is also associated with a pro-inflammatory state, reflected in the elevation of others biomarkers such as CRP." (PMID 35053667, 2022). "Alternatively, obesity is associated with higher CRP via an increased mechanical load placed on joints, leading to ‘wear and tear’ and increased expression of the pro-inflammatory cytokines (e.g., IL-1β and TNF-α) which promote CRP production." (PMID 35301057, 2022). "The values ​​of c-reactive protein, lipid and carbohydrate metabolism and liver function also improve, so weight loss also reflects a decrease in the inflammatory state linked to obesity." (PMID 35648314, 2022). "An over ten fold association with increased risk was found for CRP ≥ 21 mg/L, obesity, ESRD and saturation < 96%." (PMID 35986291, 2022). "The increased inflammation measured by serum CRP is probably caused both by synovial inflammation and inflammation due to obesity." (PMID 36307803, 2022). "Use the MR analysis method in previous sections to explore the causal relationships between thyroid signaling, CRP, and obesity traits." (PMID 35996695, 2022). "CRP is also associated with a higher risk of cardiovascular disease, as individuals with obesity and higher CRP show higher coronary artery calcium scores and increased cIMT." (PMID 36551255, 2022). "These pro-infammatory markers present high levels in OSA patients and CRP had already been associated with obesity in subjects with OSA71." (PMID 35273777, 2022). "Among the inflammatory biomarkers, the acute-phase reactant C-reactive protein (CRP) is considered the major factor associated with overweight and obesity in both adults and children." (PMID 35456438, 2022). "In this study, we have found that, despite the removal from the analysis of subjects with obesity, BMI was still significantly associated with CRP levels." (PMID 35811952, 2022). "Obesity is linked to elevated levels of inflammatory serum markers such as C-reactive protein (CRP), interleukin-6 (IL-6), and tumor necrosis factor alpha (TNFa)." (PMID 35679338, 2022). "Obesity, insulin resistance, and type 2 diabetes are closely associated with chronic inflammation, especially with the levels of CRP." (PMID 35927639, 2022).
Obesity (continued). "We prospectively examined the mediation effects of the fasting triglyceride-glucose (TyG) index and C-reactive protein (CRP) on the associations of obesity (general and abdominal) with CRC risk among 93,659 participants." (PMID 36407320, 2022). "This is because poor oral hygiene aside from causing an inflammatory response within the oral cavity, also causes increase in the levels of C reactive protein, which has been linked with the obesity." (PMID 35902918, 2022). "Obesity is characterized by a state of chronic inflammation, and it has been documented that C-reactive protein is strongly associated with the pathology." (PMID 35887894, 2022). "Third, obesity is associated with chronic inflammation due to increased pro-inflammatory cytokines and leptin by adipocytes and immune cells, including elevated C-reactive protein, interleukin 6, and ferritin." (PMID 35945221, 2022). "It was shown that obesity through its association with systemic inflammation with high levels of C-reactive protein is a mediator of fatal outcomes in SARS-CoV-2 infection." (PMID 35807129, 2022). "Many studies have confirmed the association between high BMI scores and abnormalities in these parameters and obesity, hypertriglyceridemia, and elevated CRP are also associated." (PMID 35627363, 2022). "SNVs within ENPP1 are associated with traits relevant to metabolic syndrome (blood phosphate measurement and c-reactive protein measurement), cardiovascular diseases, obesity, increased risk of glucose intolerance and type 2 diabetes in humans." (PMID 35380657, 2022). "Although the direct relationship between LLS and CRP was significant, the results of the SEM analysis showed that the association between LLS and CRP was fully mediated by BMI, hip, and waist circumferences, all markers of obesity." (PMID 35629167, 2022). "C-reactive protein (CRP) is a systemic inflammatory marker associated with obesity, insulin resistance, and cardiovascular disease." (PMID 35800023, 2022). "Another key marker of inflammation in the body is C-reactive protein (CRP), and elevated levels of CRP have been implicated in several disorders, such as obesity, T2DM, and CVDs." (PMID 36145270, 2022). "For instance, obesity is the most common risk factor for OSA and obesity has also been shown to have an impact on cytokines including CRP and TNF-α." (PMID 35652886, 2022). "In the presence of obesity, CRP levels increase, and elevated levels are associated with inflammation and insulin resistance." (PMID 36313082, 2022). "Accordingly, we suspected that the positive association between our obesity measure and CRP was likely to be driven by an increased deposition of centrally stored visceral adipose tissue." (PMID 35301057, 2022). "This paradigm is partially supported by a recent 2022 single-center retrospective study, where obesity was associated with lower rates of vedolizumab discontinuation, CRP normalization and higher rate of endoscopic remission." (PMID 36687448, 2022). "When analyzing the individual components of MUO, periodontitis was associated with elevated CRP among the US and Korean populations with overweight and obesity." (PMID 36432625, 2022). "Diets predominant in plant foods decrease obesity-related inflammatory markers, such as CRP and IL-6, which are associated with disease." (PMID 36296997, 2022). "There is a trend in the studies denoting higher CRP levels in patients with obesity and a positive association with adiposity." (PMID 35837843, 2022). "To date, these results have been conflicting, but appear to suggest an association between elevated CRP levels and obesity in older individuals and females." (PMID 36177015, 2022). "Stem cell growth factor-beta (SCGF-β) is associated with the severity of IR in a CRP-dependent manner in male patients with obesity." (PMID 36457551, 2022).
Obesity (continued). "Obesity has been linked to increased production of several cytokines, including C-reactive protein (CRP), tumor necrosis factor alpha (TNF-α), and interleukin-6 (IL-6)." (PMID 35941593, 2022). "For example, in a cross-sectional analysis, Stenholm and colleagues, observed an attenuated association between obesity and walking limitation once CRP was accounted for." (PMID 35301057, 2022). "After adjusting for sex and baseline confounders, obesity at 33y was associated with higher CRP at 45y and poor PF at 50y." (PMID 35301057, 2022). "In the present study, adjustment for CRP exerted the greatest attenuating effect (about 20 %) on the identified obesity-depressive symptom associations, supporting a potential mediating role of systemic inflammation." (PMID 35853559, 2022). "Excess adipose tissue and obesity are also associated with an increase in inflammatory markers, such as C-reactive protein (CRP), and a decrease in adipokines with anti-inflammatory properties such as adiponectin." (PMID 35742148, 2022). "Herein, we show the elevated dectin-1 gene/protein expression in the subcutaneous adipose tissue in humans with obesity to be associated positively with BMI, body fat percentage, and CRP levels in those individuals." (PMID 36139454, 2022). "In accordance with previous reports, we observed a strong correlation between maternal BMI and CRP, with overweight and obesity being associated with elevated levels." (PMID 35393396, 2022). "The group also includes the inflammation marker CRP, which is elevated in both obesity and CVD, and GAS6, which has been implicated in atherosclerosis, thrombosis and innate immune reactions." (PMID 35454109, 2022). "In this study of postmenopausal women, we quantified the mediating effects of leptin and CRP, fasting insulin, and estradiol in explaining the associations between obesity and ER‐positive breast, endometrial, and colorectal cancers." (PMID 35048536, 2022). "In this context, it is noteworthy to mention that obesity and altered CRP levels were associated with an increased risk for liver cancer." (PMID 35109885, 2022). "Levels of CRP are associated with increasing body mass index (BMI) and body fat, which is linked to obesity-induced low-grade inflammation." (PMID 35277071, 2022). "CRP has been strongly associated with overweight and obesity in human epidemiological studies and is considered a consequence of obesity rather than the cause." (PMID 36558394, 2022). "In a recent review, Puzhko and colleagues pointed out, that obesity goes in line with low-grade inflammation such as C-reactive protein (CRP) and that inflammation was linked to an altered antidepressant treatment response." (PMID 35212862, 2022). "Obesity indices were associated with leptin and CRP in the third and fourth quartiles in single models." (PMID 33680494, 2021). "Inflammation and the consequent presence of cytokines, like the tumor necrosis factor-α, monocyte chemotactic protein-1, C-reactive protein, and interleukins, are caused by obesity and are strongly associated with insulin resistance." (PMID 34829598, 2021). "Many factors are associated with baseline CRP levels, including age, sex, lifestyle, blood pressure, and in particular, metabolic risk factors such as elevated blood lipids and obesity." (PMID 34925360, 2021). "On the other hand, these metabolic parameters were significantly associated with disease duration, CV history, CRP, obesity, PWV, and IMT (p < 0.05)." (PMID 34680168, 2021). "Plasma levels of CRP and IL-6 correlated (r = −0.429) with the degree of obesity (r = 0.282) and suggested that IL-6 is associated with developing metabolic diseases." (PMID 33579000, 2021). "Overall, these studies found that wholegrain dietary intake was associated with lower levels of CRP in a female cohort with obesity and in healthy males and females as well as IL-17F in males and females from cohorts with and without underlying pathologies." (PMID 34825233, 2021).
Obesity (continued). "After adjusting for age, sex, obesity, HT, DM, DL, smoking, alcohol intake and CRP, ASM% remained associated with the risk of MetS (Model 5)." (PMID 33739984, 2021). "Our study also showed that all three body composition parameters (obesity, visceral adiposity, and sarcopenia) were associated with increased MS risk after adjustments for age, sex, HT, DM, DL, smoking, alcohol intake, and CRP levels." (PMID 34403431, 2021). "Secondly, we did not measure other inflammatory markers associated with hepcidin-25 or degree of obesity, such as CRP, IL-6, or erythrocyte sedimentation rate." (PMID 34258058, 2021). "Obesity is also associated with chronic low-grade inflammation, especially by elevations in C-reactive protein (CRP) and other proinflammatory cytokines in obese individuals as compared to lean individuals." (PMID 34436472, 2021). "Increased serum CRP level has been strongly linked to long-term health risks in women with obesity and type 2 diabetes and cardiovascular disease (CVD)." (PMID 33800490, 2021). "In particular, the first study found an association between wholegrain intake and lower levels of CRP in a female only cohort of participants with obesity." (PMID 33503979, 2021). "Obesity‐induced meta‐inflammation is associated with systemic increases in circulating inflammatory cytokines and acute phase proteins such as CRP and recruitment of leucocytes to inflamed tissues." (PMID 33851033, 2021). "Ferritin levels were significantly, positively associated with red and processed meat consumption and hs-CRP levels with obesity." (PMID 34439443, 2021). "After adjustment for age, sex, obesity, HT, DM, DL, smoking, alcohol intake and CRP, sarcopenia remained significantly associated with MetS (OR 2.291, CI 1.874–2.801, P < 0.001, Model 5)." (PMID 33739984, 2021). "In the present study, the association between obesity indices (BMI, WC, and %BF), leptin and low‐grade inflammation (CRP, IL‐6, TNF‐α) in a Zanzibari population of individuals aged 5 years and above was investigated." (PMID 33680494, 2021). "CRP is a marker of chronic low-grade systemic inflammation associated with obesity and insulin resistance." (PMID 34110438, 2021). "While CRP seemed to be linked to obesity, the other parameters were considered related to PCOS itself, including the lowering of B12, which has an anti-inflammatory action." (PMID 33562271, 2021). "This meta-analysis aimed to evaluate the effects of probiotics on body weight, body mass index (BMI), percentage of the excess weight loss (%EWL), waist circumference (WC), and C-reactive protein (CRP) in adults with obesity after bariatric surgery (BS)." (PMID 33859706, 2021). "One SNP near SALL1, in relation to CRP, both overall and in the obesity strata, is associated with breast cancer risk." (PMID 33441805, 2021). "In a study, they found that SNPs in the IL-38 gene were associated with high serum levels of CRP in patients with obesity and T2DM." (PMID 34830435, 2021). "After adjusting for age, sex, obesity, HT, DM, DL, smoking, alcohol intake, and CRP, the risk of MetS decreased by 25% per 1Q increment in ASM% (P < 0.001)." (PMID 33739984, 2021). "After adjustment for age, sex, obesity, HT, DM, DL, smoking, alcohol intake, and CRP, sarcopenia remained significantly associated with MetS." (PMID 33739984, 2021). "Obesity is associated with chronic low-grade inflammation, high leptin and C-reactive protein (CRP), and altered immune responses." (PMID 34707619, 2021). "Higher AST was significantly associated with male sex, obesity, presence of chronic liver disease and liver cirrhosis, higher CRP, and higher ferritin (p < 0.05 for all analyses)." (PMID 34575333, 2021). "A significant association is seen between higher cardiometabolic risk, inflammation (indicated by elevated CRP levels), and obesity in the participants consuming the lowest quantity of EPA and DHA versus participants in the highest quartile." (PMID 34371950, 2021).
Obesity (continued). "The distinct gut microbial composition in adults with obesity was associated with inflammation, as reflected in increased high-sensitivity C-reactive protein (CRP) plasma levels." (PMID 34938153, 2021). "In this population, besides PD also plaque revealed a strong association with CRP along with the impact of obesity." (PMID 32827080, 2021). "In the present study, leptin showed associations with disease activity, CRP, CV history, obesity, IMT, and PWV indicating that leptin indeed forms a bridge between inflammation and atherosclerosis." (PMID 34680168, 2021). "Obesity, particularly visceral adiposity, is associated with chronic low-grade inflammation, as indicated by increased levels of the inflammatory markers CRP and interleukin (IL)-6 in the circulation of obese subjects." (PMID 34828861, 2021). "Obesity is also associated with increased circulating concentrations of inflammatory markers such as C-reactive protein (CRP), interleukin-6 (IL-6), and tumor necrosis factor (TNF)-α." (PMID 33498671, 2021). "A gender influence on serum CRP measurements in periodontal disease was evidenced, with an association between CRP and probing depths mainly in men, and between overweight and obesity mainly in women." (PMID 34439905, 2021). "In parallel, fibrinogen has also been associated with hs-CRP in children with overweight and obesity." (PMID 33669882, 2021). "After adjustment for age, sex, obesity, HT, DM, DL, smoking, alcohol intake and CRP, sarcopenia remained significantly associated with MetS (OR 3.073, CI 2.009–4.701, P < 0.001, Model 5)." (PMID 33739984, 2021). "The second reason involves inflammatory factor stimulation, as obesity can cause adipose cells to secrete inflammatory factors, such as C-reactive protein, interleukin 6 (IL-6), IL-10, and tumor necrosis factor (TNF-α)." (PMID 35004287, 2021). "There are the limitations inherent to cross-sectional study designs preventing data from drawing causal inferences about the relationship between obesity and CRP levels." (PMID 32827080, 2021). "In this population-based study, we confirmed that both obesity and periodontitis are associated with higher systemic CRP and fibrinogen levels with distinct differences regarding their relative contributions." (PMID 32827080, 2021). "They demonstrated a significant association between CM and elevated CRP (defined as >3mg/dl) which remained significant in extensively adjusted models, including adjustments for adult health behaviours and obesity (RR = 1.76, 95% CI = 1.23–2.51)." (PMID 33831008, 2021). "Further, obesity is associated with the condition of chronic low-grade inflammation, characterized by an increase in some inflammatory markers such as CRP." (PMID 33921787, 2021). "Aberrant levels of CRP and procalcitonin are associated with obesity and adverse metabolic outcomes also in children." (PMID 33986456, 2021). "Even after adjustment for age, sex, obesity, HT, DM, DL, smoking, alcohol intake and CRP, the risk of MetS significantly decreased by 25% per 1Q increase of ASM%." (PMID 33739984, 2021). "Obesity is associated with elevated markers of peripheral inflammation such as CRP and IL-6, and CM is associated with increased risk of obesity." (PMID 33831008, 2021). "Obesity is also associated with increased levels of circulating pro-inflammatory markers such as CRP, IL6, TNFalpha and other cytokines." (PMID 34154662, 2021). "With respect to the immune response, there is a clear association between obesity and basal inflammatory status characterized by higher circulating Interleukin 6 and CRP levels." (PMID 33761466, 2021). "In particular, obesity and insulin resistance have been shown to be positively associated with increased levels of CRP and cytokines in numerous studies." (PMID 35601749, 2021). "In a second step, a quasi‐linear association of obesity indices with leptin, CRP, IL‐6, and TNF‐α was investigated." (PMID 33680494, 2021).